MDM2 (MDM2 proto-oncogene)
Diseases named in the same sentence as MDM2 in open-access papers (continued):
Sharing a sentence is not in itself a finding about the gene and the disease.
cancer (continued). "SAR405838 is a potent and specific MDM2 inhibitor currently being evaluated in Phase I clinical trials for the treatment of human cancer." (PMID 26070072, 2015). "This protein is overexpressed in many cancers and small-molecules that recognize MDM2 have been developed over the last decade as possible novel anti-cancer agents." (PMID 26046940, 2015). "After translocation into the nucleus, NFAT1 transactivates its downstream target genes, e.g., c-Myc, COX-2, and MDM2, resulting in cancer cell proliferation and migration." (PMID 26461225, 2015). "Several cancer cell lines with inverse expression of Set7/9 and Mdm2 displayed diminished survival in response to genotoxic stress." (PMID 26317544, 2015). "The functional single nucleotide polymorphism (SNP) in the MDM2 promoter region, SNP309, is known to be associated with various diseases, particularly cancer." (PMID 26293665, 2015). "While the regulation of XIAP expression is well characterized at the translational level, the expression of MDM2, in particular in cancer cells, is not fully understood." (PMID 25888903, 2015).
cancer (continued). "Recent years have seen intense research efforts aimed at the design and development of MDM2 inhibitors as a new class of therapeutic agents for the treatment of human cancer." (PMID 26070072, 2015). "Despite studies characterizing MDM2-ALT1 as a dominant negative regulator of full-length MDM2 and its pervasiveness in various cancers, there is very little known about the regulation of MDM2 alternative splicing in cancer and under stress." (PMID 25845590, 2015). "In an effort to screen small molecule inhibitors of MDM2 for the development of novel and effective cancer therapeutics, we identified a potent and selective MDM2 inhibitor, termed JapA." (PMID 26461225, 2015). "MDM2 has been demonstrated as a promising molecular target for cancer therapy and many MDM2 inhibitors have been developed as new anticancer drugs." (PMID 26461225, 2015). "We found that, despite not having representatives of their families, TLR7, BCL2, EZH2, and MDM2 for example, scored highly using the druggability models (74% or higher using the all-drug-target model; and 85% or higher using the cancer-drug-target model)." (PMID 26699810, 2015). "Our studies suggested that the cell lines containing higher endogenous expression levels of MDM2 have a better cell response to JapA, which contributes to the specificity of JapA in inhibiting cancer cells." (PMID 25739118, 2015). "It has also been observed that JapA is safe and effective in treating other human cancers containing high expression levels of MDM2, e.g., Burkitt lymphoma and lung cancer." (PMID 26461225, 2015).
cancer (continued). "In the context of clinical cancer metastasis, different outcomes of MDM2 expression were reported in various tissues." (PMID 26416355, 2015). "Cancer cells with MDM2 gene amplification were most sensitive to Nutlin-3 in vitro and in vivo, but Nutlin-3 also showed good efficacy against tumors with normal MDM2 expression." (PMID 26125230, 2015). "While clinical development of several MDM2 inhibitors is in progress in cancer therapy, the biological impact of autophagy in their responses need to be explored." (PMID 26440941, 2015). "As MEL23/MEL24 strongly stabilize Mdm2 and MdmX,55 our MMRi64 has unique property for better targeting oncogenic Mdm2–MdmX complex for robust cancer cell killing." (PMID 26720344, 2015). "While MDM2 inhibitors hold great potential as cancer therapeutics, the ability to predict which tumors will respond to these agents will be critical to realizing this promise." (PMID 25730903, 2015). "Applying this cutoff resulted in a pan-cancer MDM2 amplification rate far lower than previously published." (PMID 25730903, 2015). "Non-genotoxic small molecule inhibitors targeting this interaction such as Nutlin-3 are reported to have some efficacy in cancers with MDM2 overexpression." (PMID 26416444, 2015).
cancer (continued). "Future studies to identify other modifiers of MDM2 splicing will enable a comprehensive understanding of stress, cancer-induced splicing, and the design of specific splicing modulation strategies." (PMID 25845590, 2015). "Both natural and synthetic MDM2 inhibitors have been shown anticancer activity against several human cancers." (PMID 26041888, 2015). "Such a use of Mdm2 inhibitors for avoiding the toxicities of cancer treatment is not limited to Wee1-inhibitors." (PMID 26431163, 2015). "By Min Qi and colleagues, they found that HSP40/DNAJB1 inhibited cancer cell growth in vitro and in vivo by stabilizes MDM2, which was consistent to our results although it worked though two different pathways." (PMID 24658033, 2014). "In case of Rb, USP7 shows a differential deubiquitination in normal and cancer (glioma) cells depending on the Mdm2 levels." (PMID 25121098, 2014). "While MDM2 inhibitors hold great promise as cancer therapeutics, drug resistance will likely limit their efficacy as single agents." (PMID 24810962, 2014). "In response to genotoxic stress and also in several cancer types, MDM2 and MDMX are alternatively spliced." (PMID 25105592, 2014). "MDM2, OPN and other genes linked to cancer provide evidence for the apoptotic and cell cycle regulatory pathways that are likely the molecular mechanisms of inflammation, proliferation and liver damage in aflatoxicosis." (PMID 24979717, 2014).
cancer (continued). "Some cancer cells expressing high levels of MDM4 are reportedly resistant to small-molecule MDM2 inhibitors." (PMID 25621298, 2014). "Small-molecule MDM2 antagonists like nutlin-3 have demonstrated beneficial effects in cellular and preclinical models of various cancer types, including AML." (PMID 24885082, 2014). "MDM2 is overexpressed in a various human cancers, including melanoma, non-small cell lung cancer, breast cancer, esophageal cancer, leukemia, non-Hodgkin’s lymphoma, and sarcoma." (PMID 25009749, 2014). "There is only limited information concerning the regulation or functional significance of nucleostemin–MDM2 protein interactions in human cancer cells." (PMID 25209720, 2014). "The opposing roles played by USP7 and Mdm2 is critical for maintaining the level of Daxx in the cancer cells." (PMID 25121098, 2014).